MIF (macrophage migration inhibitory factor)
Diseases named in the same sentence as MIF in open-access papers (continued):
Sharing a sentence is not in itself a finding about the gene and the disease.
ischemic stroke (continued). "The MIF exerts a neuroprotective effect in an in vivo ischemic stroke model." (PMID 35805977, 2022). "Interestingly, MIF has been reported to have both protective and detrimental effects on ischemic stroke." (PMID 33672416, 2021). "Our previous studies have reported that MIF mainly plays a neuroprotective role in ischemic stroke." (PMID 33672416, 2021). "Early exercise could improve motor and neuronal recovery after ischemic stroke, and the increased level of MIF in the penumbra may be one mechanism of enhanced neurological function recovery." (PMID 32964038, 2020). "Here we found that the blood level of MIF in ischemic stroke patients is upregulated." (PMID 29335619, 2018). "We then examined the infarct volume of MIF in ischemic stroke model." (PMID 29335619, 2018). "This suggests that inhibition of MIF may serve as a viable strategy for the treatment of ischemic stroke." (PMID 22768247, 2012). "This suggests that inhibition of MIF may represent a suitable treatment strategy for ischemic stroke." (PMID 22768247, 2012). "Therefore, the role of MIF inhibitor ISO-1 in ischemic stroke deserves further study." (PMID 36797398, 2023). "Thus, high MIF K78 acetylation may contribute to neuronal protection after ischemic stroke and potentially other neurodegenerative diseases." (PMID 35585040, 2022). "Considering that serum MIF levels after ischemic stroke have been shown to peak within the first 24 h after ictus, this difference could be attributable to our sampling window for EPd1−4, which comprised the first 4 days after hemorrhage but not the day of aSAH onset." (PMID 36712451, 2022). "Indeed, the implication of MIF in ischemic stroke has been revealed." (PMID 29335619, 2018). "Therefore, the higher expression of astrocyte may correlate with the severity of ischemic stroke in MIF-treated rats." (PMID 29335619, 2018). "In our study, the concentration of chemotactic factors (CTACK, IL-8, MIG, MIF) and growth factors (basic FGF, G-CSF, HGF, LIF, VEGF) was significantly higher in the unstimulated saliva of patients with ischemic stroke compared to the control group." (PMID 40221607, 2025). "We further demonstrated that MIF K78 acetylation attenuated the interaction between MIF and AIF, resulting in impairment of MIF nuclear translocation and therefore protecting neurons from ischemic stroke." (PMID 35585040, 2022). "Moreover, the MIF K78R mutant reversed the protective effect of HDAC6 inhibition and aspirin treatment in response to ischemic stroke." (PMID 35585040, 2022). "Considering that TNF, SPP1, MIF, and GALECTIN signaling pathways are involved in various forms of programed cell death (PCD), we hypothesized that PANoptosis contributes critically to ischemic stroke pathology." (PMID 41235394, 2025). "One such cytokine is macrophage migration inhibitory factor (MIF), which was shown to be elevated on circulating myeloid cells in patients after surgery and in mice subjected to peripheral surgery followed by middle cerebral artery occlusion (MCAO), a model of perioperative ischemic stroke." (PMID 38347307, 2024). "Finally, this study did not evaluate the long-term effect of the MIF effects, and further study evaluating long-term effects to elucidate pro-inflammatory processes after ischemic stroke are needed." (PMID 35805977, 2022). "Furthermore, these results suggest that MIF is neuroprotective in ischemic stroke mainly via the inhibition of apoptosis rather than through BDNF-associated mechanisms." (PMID 33672416, 2021). "HDAC6 is known to deacetylate non-histone proteins, such as macrophage migration inhibitory factor (MIF), and its inhibition by TubA markedly increases MIF acetylation, a modification that contributes to its neuroprotective function in ischemic stroke models." (PMID 40867911, 2025). "Finally, the non-cooperatively expressed MIF was removed, and PTGS2, MAP1LC3B, and TLR4 were further selected as ferroptosis-related biomarkers for ischemic stroke." (PMID 34707562, 2021).
myocardial ischemia (20 papers, 2012 to 2025). A disorder of cardiac function caused by insufficient blood flow to the muscle tissue of the heart. "Association of MIF in myocardial ischemia and infarction has been reported in clinical and experimental settings." (PMID 36035926, 2022). "Elevated levels of MIF in plasma can serve as an early biomarker for acute myocardial ischemia and can be risk factor for future coronary events in IHD patients with T2DM." (PMID 35663309, 2022). "The increased susceptibility of myocardial ischemia of older patients with history of cardiovascular disease may be attributed to an impaired MIF-AMPK activation response so upregulation of AMPK through targeting of MIF could provide a new treatment for these patients." (PMID 27478687, 2014). "MIF is reported to have both protective and proinflammatory effects in myocardial ischemia and infarction." (PMID 40092999, 2025). "Macrophage inhibitory factor (MIF) is a pro-inflammatory cytokine which has also been shown to be a key mediator of cardiac fibrosis, particularly in the context of myocardial ischemia." (PMID 39505939, 2024). "Conversely, when myocardial ischemia is prolonged, MIF activates immune cells, thereby increasing inflammation and cardiac remodeling by utilizing myofibroblasts to promote matrix protein synthesis." (PMID 38476376, 2024). "For instance, when cardiac ischemia is brief, MIF secreted by cardiomyocytes is cardioprotective through activation of AMP-activated protein kinase (AMPK)." (PMID 38476376, 2024). "This indicates that the early surge of MIF level, which actually reflects the extent of acute myocardial ischemia/necrosis, likely masks its difference as an inflammatory biomarker between the non-MetS and MetS groups." (PMID 36035926, 2022). "In the setting of extended myocardial ischemia, reflected by our model of permanent coronary artery ligation, MIF has been found to be pro-inflammatory and to contribute to cardiac dysfunction and remodeling." (PMID 35563680, 2022). "Third, MIF was described as an angiogenic factor in experimental models of myocardial ischemia and reperfusion and was attributed to mitogen-activated protein kinase (MAPK) and phosphoinositide 3-kinase (PI3K) signaling." (PMID 29027966, 2017). "Second, MIF is a regulator of apoptotic processes via the inhibition of the stress kinase c-Jun N-terminal kinase (JNK) which is activated by myocardial ischemia and reperfusion." (PMID 29027966, 2017). "MIF was shown to be cardioprotective in experimental myocardial ischemia/reperfusion injury and its expression is regulated by the transcription factor hypoxia-inducible factor (HIF)-1α." (PMID 29027966, 2017). "Over the past decade a number of studies have demonstrated that MIF regulates key functions during myocardial ischemia/reperfusion injury with an overall cardioprotective effect." (PMID 24667295, 2014). "In conclusion, recent data indicate that similarly as CXCR4, MIF plays a double-edged role in myocardial ischemia." (PMID 24966838, 2014). "Recently, the pleiotropic cytokine macrophage migration inhibitory factor (MIF) has emerged as a promising mediator providing cardioprotection during myocardial ischemia and reperfusion." (PMID 24667295, 2014). "In myocardial ischemia, MIF could enhance cardiac health protection by activating AMP-activated protein kinase (AMPK)." (PMID 40724906, 2025). "With the exacerbation of myocardial ischemia and infarction, MIF promotes the accumulation of macrophages and other inflammatory cells in damaged necrotic myocardium, upregulates an inflammatory response, and induces the production of other inflammatory factors, aggravating myocardial damage." (PMID 30983881, 2019). "Also, CXCR4 can form receptor complexes with CD7430,61, and MIF/CD74 signaling has important cardioprotective activities in myocardial ischemia/reperfusion injury." (PMID 29581527, 2018).
myocardial ischemia (continued). "To date, the HIF-1α/MIF axis has been investigated in multiple experimental models including cardiomyocyte and smooth muscle cell cultures after induction of hypoxia, in mouse models of myocardial ischemia/reperfusion injury, and in cancer." (PMID 29027966, 2017). "Importantly, MIF is not only a mediator of inflammatory processes, but also a key player in myocardial ischemia and reperfusion injury and has recently been identified as a potent cardioprotective factor." (PMID 29027966, 2017). "Therefore, it is suggested that elevated post-ischemic MIF levels exacerbate ischemic tissue damage after myocardial ischemia and reperfusion." (PMID 26577797, 2015). "We will address the double-edged role of MIF in myocardial ischemia below." (PMID 24966838, 2014). "Thus, upon acute myocardial ischemia and MI, cardiac cells are able to promptly release into circulation not only MIF, also other inflammatory molecules like IL-6." (PMID 24098445, 2013).
bladder cancer (19 papers, 2007 to 2025). "In terms of diagnostic and prognostic utility, MIF demonstrates potential as a biomarker for bladder cancer." (PMID 41159021, 2025). "In “Validation analyses” appraising previously reported inflammatory marker-cancer risk relationships, we found suggestive evidence for an association of genetically-proxied macrophage migration inhibitory factor concentrations with bladder cancer risk." (PMID 38301482, 2024). "MIF KO mice developed consistently lower stage tumors with less associated angiogenesis in a BBN model of bladder cancer." (PMID 17650334, 2007). "For instance, it was found that Urinary bladder cancer (UBC) was shown to have considerably higher serum MIF levels than urinary bladder disease (UBD) and higher than normal patients indicating that MIF could be a potential diagnostic marker for bladder cancer." (PMID 41159021, 2025). "In another study it was shown that chimeric transcript SLC2A11 (solute carrier family 2 member 11)–MIF promoted metastasis, proliferation and inhibited apoptosis in bladder cancer cells via PTBP1 (Polypyrimidine tract binding protein)-dependent mechanism." (PMID 41159021, 2025). "According to a study, it was reported that MIF can increase proliferation and growth of bladder cancer cells via ERK pathway and also enhances angiogenesis via increasing the expression of VEGF (Vascular endothelial growth factor)." (PMID 41159021, 2025). "Another study reported that MIF was negatively correlated with overall survival rate in bladder cancer, highlighting its prognostic relevance." (PMID 41159021, 2025). "Further, in animal models of bladder cancer, MIF knockout mice displayed decreased angiogenesis and invasion as compared with wild-type mice and those administered oral MIF inhibitors had decreased growth and progression of tumours as compared to controls." (PMID 38301482, 2024). "4-IPP treatment in murine bladder cancer models resulted in decreased tumor weights in MIF-KO versus WT mice, suggesting an additive contribution of DDT inhibition." (PMID 38732068, 2024). "In vitro studies indicated that the presence VIP in high doses reduced MB49 cell growth, as well as macrophage inhibitory factor (MIF), a growth factor in bladder cancer cells." (PMID 28824540, 2017). "Compared to cells grown in the absence of VIP, those grown in the presence of VIP also showed decreased extracellular MIF accumulation, a molecule known to promote proliferation of bladder cancer cells." (PMID 28824540, 2017). "We have preliminary data from human bladder cancer specimens showing similar redistribution of MIF to the nucleus when compared to benign tissue." (PMID 17650334, 2007). "Macrophage migration inhibitory factor (MIF) is a proinflammatory cytokine with regulatory properties over tumor suppressor proteins involved in bladder cancer." (PMID 17650334, 2007). "This is the first report of the impact of MIF gene deletion on the development and progression of bladder cancer." (PMID 17650334, 2007). "Recently, inhibition of MIF with hyaluronic acid, anti-MIF antibody or MIF anti-sense, was shown to decrease in vitro bladder cancer cell proliferation and cytokine expression." (PMID 17650334, 2007). "Anti-MIF antibody reduced the proliferation in HT-1376 cell (human bladder cancer cell)." (PMID 41159021, 2025). "MIF-KO murine bladder cancer models demonstrated decreased vascularization and tumor stage." (PMID 38732068, 2024). "Consequently, the putative role of MIF in development of bladder cancer is unclear and requires further evaluation in future studies." (PMID 38301482, 2024). "In replication analysis of the association of macrophage migration inhibitory factor with bladder cancer risk, there was little evidence of association with large heterogeneity (I2 = 83.6%) across studies." (PMID 38301482, 2024). "In bladder cancer cells, MIF knockdown produced a dose-dependent reduction in growth." (PMID 38732068, 2024).
bladder cancer (continued). "Though the association with bladder cancer risk was not consistent in replication analyses in FinnGen, there was evidence that the SNP used to instrument macrophage migration inhibitory factor concentrations (rs2330634) was an eQTL for MIF in 35 tissue types." (PMID 38301482, 2024). "In the N-butyl-N-(4-hydroxybutyl)-nitrosamine (BBN) model, MIF accelerates bladder cancer by promoting cell proliferation and angiogenesis, so MIF inhibitors may be a helpful treatment in the field of this disease." (PMID 35806303, 2022). "We hypothesized that VIP would decrease cell growth by decreasing the activity of macrophage inhibitory factor (MIF), a known growth factor in bladder cancer cells." (PMID 28824540, 2017). "Our results suggest that MIF may be involved in the progression of bladder cancer to muscle invasion." (PMID 17650334, 2007). "In bladder cancer, they actively communicate with surrounding cells through enhanced extracellular matrix-related signals such as collagen and laminin, as well as immune regulatory signals like MIF, constructing ecological niches favorable for their survival and immune exemption." (PMID 41373831, 2025). "Furthermore, it was reported that MIF was increased in muscle invasive bladder cancer and this indicates that MIF could be involved in bladder cancer invasion and migration." (PMID 41159021, 2025). "In colocalisation analysis, there was evidence to support shared causal variants across circulating MIF concentrations and bladder cancer risk in the MIF locus (PPH4 = 76.1%), but little evidence to suggest shared causal variants across 5 other inflammatory marker-cancer associations." (PMID 38301482, 2024). "We studied the development of bladder cancer in wild type (WT) and MIF knockout (KO) mice given N-butyl-N-(4-hydroxybutyl)-nitrosamine (BBN), a known carcinogen, to determine the role of MIF in bladder cancer initiation and progression." (PMID 17650334, 2007). "MIF and DDT overexpression has been observed in TCGA analysis of bladder cancers." (PMID 38732068, 2024).
pulmonary hypertension (19 papers, 2012 to 2026). Increased pressure within the pulmonary circulation due to lung or heart disorder. "Currently, some studies have linked MIF concentration to particular SSc presentations, such as pulmonary arterial hypertension (PAH), impaired lung function, and ACE inhibitor usage, although not all studies have confirmed this." (PMID 38790215, 2024). "MIF was associated with clinical outcomes and might be involved in the pathophysiology of pulmonary hypertension in patients with HFpEF." (PMID 29728137, 2018). "Our results showed that preoperative exposure to respiratory viruses and postoperative overexpression of IL-1/IL-1RA, MIF and MCP-1 acted as combined risk factors for postoperative pulmonary hypertension." (PMID 36670454, 2023). "Another important proinflammatory cytokine is macrophage migration inhibitory factor (MIF), which was upregulated in the lungs of rats with chronic hypobaric hypoxia-induced pulmonary hypertension." (PMID 36293512, 2022). "Serum levels of MIF were increased in patients with IPF combined with pulmonary hypertension, and MIF levels in lung tissues and bronchoalveolar lavage fluids (BALF) were significantly increased in the murine model of bleomycin-induced pulmonary fibrosis." (PMID 32694925, 2020). "Curative treatments with the MIF antagonist ISO-1 or anti-CD74 neutralizing antibodies partially reversed the development of pulmonary hypertension and substantially reduced inflammatory cell infiltration in the rat monocrotaline model of PAH." (PMID 33105588, 2020). "Clinical studies demonstrated elevated MIF concentration in patients suffering from pulmonary hypertension." (PMID 30856182, 2019). "MIF was shown to stimulate pulmonary artery smooth muscle cell proliferation in hypoxic pulmonary hypertensive rats, an effect that involves ERK 1/2 and JNK phosphorylation." (PMID 30881226, 2019). "Animal studies showed that antibodies directed against MIF reversed hypoxia-induced pulmonary hypertension in mice and in rats." (PMID 30856182, 2019). "Macrophage migration inhibitory factor (MIF) plays an important pathophysiological role in pulmonary hypertension (PHT)." (PMID 30881226, 2019). "A recently developed MIF antagonist was even able to attenuate monocrotaline-induced pulmonary hypertension in rats." (PMID 29728137, 2018). "Preclinical data using different anti-MIF’s in different animal models with chronic and severe forms of pulmonary hypertension are very promising." (PMID 30083544, 2018). "In experimental models, treatments with the MIF antagonist ISO-1 or anti-CD74 neutralizing antibodies partially reversed development of pulmonary hypertension in rats and substantially reduced inflammatory cell infiltration." (PMID 29728137, 2018). "In infants with CHD, several inflammatory molecules, such as RANTES and macrophage migration inhibitory factor (MIF) related to pulmonary congestion or pulmonary vascular resistance, respectively—mechanisms known to be involved in the pathophysiology of pulmonary hypertension." (PMID 34855062, 2022). "MIF is increased in patients with mild and severe SARS-CoV-2 and may be associated with impaired organ function and increased pulmonary arterial hypertension." (PMID 36110852, 2022). "Thus, these two characteristics of MIF alone make it a molecule of interest in the development and progression of pulmonary arterial hypertension." (PMID 30083544, 2018). "We conclude that MIF contributes to the hypoxic pulmonary hypertension, but further studies will be needed to extend these findings, with the aim of identifying new therapeutic targets for treatment of pulmonary hypertension." (PMID 22363104, 2012). "Since recent studies utilizing either echocardiography or right heart catheter indicated a pulmonary hypertension prevalence in a range between 36 and 83%, further studies should investigate whether MIF serves a role in the right heart pathophysiology in HFpEF." (PMID 29728137, 2018).